IMPA2 (inositol monophosphatase 2)
Description:
Phosphatase that can use myo-inositol monophosphates, myo-inositol 1,4-diphosphate, scyllo-inositol-1,4-diphosphate, glucose-1-phosphate, beta-glycerophosphate and 2'-AMP as substrates in vitro. It is likely that IMPA2 has an as yet unidentified in vivo substrate(s). Has been implicated as the pharmacological target for lithium (Li(+)) action in brain.
Tractability: Small molecule: it has a high-quality binding pocket; it belongs to a druggable protein family. PROTAC: ubiquitination databases record sites on it.
Gene: Protein-coding gene on chromosome 18 (11,981,025 to 12,030,877, forward strand). Ensembl gene ENSG00000141401.
Subcellular location: Cytoplasm
Subcellular location (Human Protein Atlas): Nucleoplasm; Mitochondria
Pathways (Reactome):
Metabolism: Synthesis of IP2, IP, and Ins in the cytosol
Gene Ontology:
Molecular function: glucose-1-phosphatase activity; glycerol-2-phosphatase activity; inositol monophosphate 1-phosphatase activity; inositol monophosphate 3-phosphatase activity; inositol monophosphate 4-phosphatase activity; inositol monophosphate phosphatase activity; protein binding; protein homodimerization activity
Biological process: response to lithium ion; phosphate-containing compound metabolic process; signal transduction; inositol biosynthetic process; phosphatidylinositol phosphate biosynthetic process
Cellular component: cytoplasm; cytosol
Genetic constraint (gnomAD): Loss-of-function variants: 24 observed, 27.56 expected, observed/expected ratio (o/e) 0.87, 90% interval 0.63 to 1.23. The upper end of that interval is the gene's LOEUF score, 1.23, which puts it in group 5 of 6, group 1 being the genes least tolerant of losing a copy. Missense variants: 311 observed, 355.43 expected, observed/expected ratio (o/e) 0.88, 90% interval 0.8 to 0.96. Synonymous variants: 125 observed, 145.26 expected, observed/expected ratio (o/e) 0.86, 90% interval 0.74 to 1.
Homologues: Orthologues: chimpanzee IMPA2 (99% identical), macaque IMPA2 (99% identical), mouse Impa2 (91% identical), rat Impa2 (90% identical), pig IMPA2 (90% identical), dog IMPA2 (86% identical), guinea pig IMPA2 (80% identical), tropical clawed frog impa2 (77% identical), zebrafish impa2 (66% identical), Drosophila melanogaster CG17028 (34% identical), Drosophila melanogaster CG17029 (33% identical), Drosophila melanogaster CG17026 (31% identical), and 1 more. Paralogues in human: IMPA1 (51% identical), BPNT1 (23% identical), INPP1 (22% identical), BPNT2 (21% identical).